RGL4 (ral guanine nucleotide dissociation stimulator like 4)
Synonyms: RGR
Tractability: Antibody: its Gene Ontology location is reachable by antibodies, with medium confidence. PROTAC: ubiquitination databases record sites on it.
Gene: Protein-coding gene on chromosome 22 (23,688,136 to 23,699,176, forward strand). Ensembl gene ENSG00000159496.
Subcellular location: Cytoplasmic vesicle
Subcellular location (Human Protein Atlas): Centrosome
Gene Ontology:
Molecular function: guanyl-nucleotide exchange factor activity
Biological process: Ras protein signal transduction; small GTPase-mediated signal transduction
Cellular component: plasma membrane; cytoplasmic vesicle
Genetic constraint (gnomAD): Loss-of-function variants: 36 observed, 45.88 expected, observed/expected ratio (o/e) 0.78, 90% interval 0.6 to 1.04. The upper end of that interval is the gene's LOEUF score, 1.04, which puts it in group 4 of 6, group 1 being the genes least tolerant of losing a copy. Missense variants: 575 observed, 582.19 expected, observed/expected ratio (o/e) 0.99, 90% interval 0.92 to 1.06. Synonymous variants: 242 observed, 235.78 expected, observed/expected ratio (o/e) 1.03, 90% interval 0.92 to 1.14.
Homologues: Paralogues in human: RALGDS (39% identical), RGL1 (29% identical), RGL3 (25% identical), RGL2 (23% identical), RAPGEF1 (18% identical), RASGRF2 (17% identical), RASGRF1 (17% identical), SOS2 (16% identical), SOS1 (16% identical), RASGEF1B (14% identical), RAPGEF2 (14% identical), RASGEF1C (14% identical), and 12 more.
Diseases named in the same sentence as RGL4 in open-access papers:
RGL4 is named in the same sentence as 6 diseases in open-access papers, as found by Europe PMC text mining. Sharing a sentence is not in itself a finding about the gene and the disease. The quoted sentences say what the papers report.
lung adenocarcinoma (2 papers, 2022 to 2023). A carcinoma that arises from the lung and is characterized by the presence of malignant glandular epithelial cells. "evidenced that the reduced expression of RGL4 was remarkably related to unfavorable prognostic results and immunocyte infiltrative activities in lung adenocarcinoma (LUAD) cases and highlighted the utilization of RGL4 as a new prediction marker for the prognostic results of LUAD." (PMID 37359526, 2023). "The roles of KLRK1 and RGL4 have not been investigated in any malignancies but have been identified as prognostic factors in lung adenocarcinoma." (PMID 35300417, 2022).
colorectal cancer (1 paper, 2021). A primary or metastatic malignant neoplasm that affects the colon or rectum. "We first analyzed the transcriptional profiling of RGL subtypes RGL1, RGL2, RGL3, and RGL4 in The Cancer Genome Atlas (TCGA) colorectal cancer (CRC) database." (PMID 33917100, 2021).
Sepsis (1 paper, 2020). Sepsis is defined as life-threatening organ dysfunction caused by a dysregulated host response to infection. "The profile is somewhat similar in pediatric sepsis with connections between GPR84 and TDRD9 directly and indirectly through instead DDAH2 and with CD177 through C19orf59 and RGL4." (PMID 32318053, 2020). "Gene entities shared between sepsis and severe sepsis response hubs are; TDRD9 – LIN7A, GPR84 – ENTPD7, PYCT1A and ZDHHC19, CD177 – DDAH2 and RGL4, SLC16A3 – DENND3 and MBD6, MYL9 – CMTM5, ITGB3, ITGA2B, NRGN, SELP and TREML1." (PMID 32318053, 2020). "These shared few commonalities between the different disease groups with the exception of DDAH2, RGL4, and ZDHHC19 in adult sepsis and pediatric septic shock." (PMID 32318053, 2020).
septic shock (1 paper, 2023). Shock caused by infection; frequently caused by gram negative bacteria, although some cases have been caused by other bacteria, viruses, fungi, and protozoa; characterized by fever, chills, tachycardia, tachypnea, and hypotension. "CD177, CLEC5A, CYSTM1, MCEMP1, MMP8, and RGL4 were identified as hub genes, which were of considerable value in the early diagnosis of septic shock patients." (PMID 37359526, 2023). "In addition, higher expression levels of CD177, CLEC5A, CYSTM1, MCEMP1, MMP8, and RGL4 messenger RNA (mRNA) were observed in peripheral blood mononuclear cells (PBMCs) isolated from septic shock patients than from healthy donors." (PMID 37359526, 2023).
cancer (2 papers, 2022 to 2023). A tumor composed of atypical neoplastic, often pleomorphic cells that invade other tissues. "The exact role of IL18RAP, RGL4 and TMC7 in cancer and its potential as a therapeutic target or marker is still not well understood, and further research is needed to determine its full implications in the development and progression of cancer." (PMID 37171396, 2023).
tumor (2 papers, 2023). "Moreover, the expression of RGL4 has been found to be correlated with a variety of tumor-infiltrating immune cells, such as neutrophils, CD8+ T cells, and memory B cells." (PMID 37359526, 2023). "HCC tumor tissues contain high levels of HMOX1, S100A9, TMC7, TRAF3 and TRIM21, whereas the expression of IL8RAP and RGL4 were higher in the control group." (PMID 37171396, 2023).